SOX11 (SRY-box transcription factor 11)
Diseases named in the same sentence as SOX11 in open-access papers (continued):
Sharing a sentence is not in itself a finding about the gene and the disease.
glioma (continued). "Compared to glioses, glial neoplasms were significantly more often positive (p < 0.001, χ2) for EGFR (33.8%), MEOX2 (48.9%), SOX11 (69.9%) and INSM1 (64.9%)." (PMID 37568909, 2023). "Glial neoplasms were significantly more often (p < 0.001, χ2) positive for EGFR (34.1% vs. 0%), MEOX2 (49.3% vs. 2.3%), SOX11 (70.5% vs. 20.4%), and INSM1 (65.4% vs. 2.3%)." (PMID 37568909, 2023). "We postulated that immunohistochemical detection of proteins expressed preferentially in gliomas (EGFR, MEOX2, CD34) or during embryonal development (SOX11, INSM1) can be used to distinguish reactive gliosis from glioma." (PMID 37568909, 2023). "After excluding IDH1 R132H mutant gliomas from the analysis, the specificity increased to 41.5% for EGFR, 53.2% for MEOX2, 50.7% for SOX11 and 57.3% for INSM1." (PMID 37568909, 2023). "On the other hand, the underexpression of LINC-ROR is correlated with the mRNA expression levels of SOX11 and KLF4 in glioma." (PMID 33745265, 2021). "Nine TAPPs from the glioma cells (Aim2, Art-4, EphA2, EZH2, Fosl1, PTH-rP, Sox11, Whsc2 and YKL-40) consistently exhibited increased mRNA presence (≥1.9-fold expression) after culturing the cells in hypoxia (1% O2)." (PMID 22957023, 2012). "Although tumors were eventually formed in the brains engrafted with glioma cells that were infected with NGN2/SOX11 virus, they grew slowly and were largely formed by noninfected GFP-negatvie cells." (PMID 25321470, 2014). "About 13% of the control GFP-infected glioma cells stained positive for Ki67, whereas no Ki67 was detected in NGN2/SOX11 virus-infected glioma cells." (PMID 25321470, 2014). "To determine whether reprogramming the fate of glioma cells has any therapeutic potential for brain tumors, we examined the effect of ectopic expression of NGN2/SOX11 on the growth of preexisting tumors." (PMID 25321470, 2014). "Many of the TAPP were not differentially expressed in the hypoxic cells but nine TAPPs from the glioma cells (Aim2, Art-4, EphA2, EZH2, Fosl1, PTH-rP, Sox11, Whsc2 and YKL-40) consistently exhibited increased mRNA presence after culturing the cells in response to hypoxia." (PMID 22957023, 2012). "As internal controls for immunohistochemistry, 16.8 and 15.5% of the non-infected (GFP−) human glioma cells were detected in mice injected with lentivirus expressing the control GFP and NGN2/SOX11, respectively." (PMID 25321470, 2014). "Although non-transduced glioma cells quickly expanded and eventually led to death of the engrafted mice, Kaplan–Meier survival analysis showed that direct injection of NGN2/SOX11-expressing virus into tumor-bearing mice significantly extended their lifespan." (PMID 25321470, 2014). "Approximately 22.2% of glioma cells infected with lentivirus expressing only NGN2 were converted to TUJ1+ neuron-like cells, while the expression of SOX11 alone did not generate any of these cells." (PMID 25321470, 2014).
lymphoma (24 papers, 2010 to 2025). A malignant (clonal) proliferation of B- lymphocytes or T- lymphocytes which involves the lymph nodes, bone marrow and/or extranodal sites. "Further study of SOX11 in MCL cells has demonstrated that high SOX11 promotes the growth of lymphoma cells and prevents differentiation." (PMID 26894864, 2016). "This series reported that nuclear SOX11 was strongly positive in most B and T-lymphoblastic leukemia/lymphomas and half of childhood Burkitt’s lymphomas, but only weak SOX11 expression was seen in hairy cell leukemia." (PMID 26949534, 2016). "Of interest, homogeneous methylation of the SOX11 promoter is more frequently observed in lymphomas compared to solid tumors." (PMID 25880212, 2015). "SOX11 has been previously studied in lymphoma and ovarian cancers and showed correlations to patients’ survival." (PMID 24604109, 2014). "The fact that SOX11 is hypermethylated and silenced in some lymphomas can lead to assume that SOX11 is a candidate tumor suppressor gene, as recently proposed by Gustavsson and coworkers." (PMID 21738649, 2011). "SOX11 was also reported to promote tumor angiogenesis in certain forms of lymphoma." (PMID 38263175, 2024). "Therefore, the staining for SOX11 in CCND1-negative CD5 expressing lymphomas is recommended to clarify the diagnosis." (PMID 34898558, 2021). "However, the studies on the expression and significance of SOX11 in malignant tumors other than lymphoma are very limited." (PMID 24604109, 2014). "SOX11 was recently discovered to be a prognostic factor in lymphoma and ovarian cancer." (PMID 24604109, 2014). "SOX11 was firstly reported in hematopoietic malignancies such as lymphoma." (PMID 24604109, 2014). "To determine whether the SOX11-C1 antibody allow intracellular detection of SOX11 in flow cytometry, we performed a proof-of-principle assay and analyzed well-defined lymphoma and EOC cell lines." (PMID 22738398, 2012). "SOX11 is a TF with important roles in brain development that is strongly upregulated in lymphoma and malignant glioma, where it may affect tumorigenesis." (PMID 21226949, 2011). "The possible role of the aberrant SOX11 expression in lymphoma is unknown." (PMID 21124928, 2010). "SOX11 has also recently emerged as a tumor marker for MCL, particularly in cyclin D1-negative MCLs and to distinguish between MCLs and other cyclin D1-positive lymphomas." (PMID 31714947, 2019). "SOX11 was negative in chronic lymphocytic leukemia/lymphoma, marginal zone, follicular and diffuse large B-cell lymphomas, as well as in cases of myeloma, Hodgkin’s lymphomas and mature T-cell and NK/T-cell lymphomas." (PMID 26949534, 2016). "As we here clearly show that SOX11 is silenced by histone modifications in normal hematopoietic cells, hypermethylation in lymphomas does not modify SOX11 expression levels, and thus, does not seem to have a functional impact." (PMID 21738649, 2011). "Currently, no specific functional effects have been linked to SOX11 expression in MCL and it is not known which genes are under influence of SOX11 in lymphoma." (PMID 21124928, 2010). "In addition, new analysis predicted lymphoma subtypes using cell-of-origin markers that hematopathologists use in the clinical routine, including CD3, CD5, CD19, CD79A, MS4A1 (CD20), MME (CD10), BCL6, IRF4 (MUM-1), BCL2, SOX11, MNDA, and FCRL4 (IRTA1)." (PMID 38745770, 2024). "Most of the genes associated with the “regulation of lymphocyte proliferation” (including SOX11) were downregulated, supporting the phenotypic observation in mice with grafted Granta-519 MCL tumors that DPN treatment impaired tumor growth by affecting lymphoma cell proliferation." (PMID 35804870, 2022). "Given the tumour suppressor function of SOX11 and the association with cell cycle status, which has been demonstrated previously by us in lymphomas, it is not surprising that the promoter region of SOX11 in some EOC cell lines becomes methylated in order to silence gene expression." (PMID 21943380, 2011).
lymphoma (continued). "As the neoplastic cells were negative for CD3, CD23, cyclin D1, Tdt, SOX11, and MUM1, the mantle and marginal zone lymphomas that can occur at this site were ruled out." (PMID 40027040, 2025). "A striking difference in SOX11 promoter methylation was detected between MCL and non-MCL lymphoma cell lines." (PMID 20624318, 2010). "However, SOX11 is not exclusive to MCL; it has also been identified in one-third of Burkitt’s lymphomas and in some cases of lymphoma /T-cell lymphoblastic leukaemia." (PMID 27110283, 2016).
B-cell lymphomas (20 papers, 2010 to 2025). "SOX11 is a diagnostic and prognostic antigen of B-cell lymphoma, and has been shown to have tumor suppressor function." (PMID 35033084, 2022). "SOX11 was recently discovered to be a diagnostic, prognostic and functionally associated antigen in B cell lymphomas, but also of prognostic value in EOC." (PMID 21943380, 2011). "SOX11 is a diagnostic and prognostic antigen in B cell lymphomas and has recently been demonstrated by us to have tumour suppressor functions." (PMID 21943380, 2011). "Recent data have suggested a functional role for the developmentally associated transcription factor SOX11 outside the CNS, and this marker has been shown to be expressed in specific subtypes of B cell lymphomas, as well as in solid tumors." (PMID 20624318, 2010). "Nevertheless, as compared to other B-cell lymphomas, with the exception for some cases of Burkitt lymphomas, the SOX11 mRNA levels in MCL is much higher." (PMID 34888236, 2021). "Most B-cell lymphomas are heavily methylated in the SOX11 promoter region while solid tumor cells show a more diverse methylation pattern." (PMID 25880212, 2015). "Our data show that the pattern of SOX11 methylation is more diverse within solid tumor types, compared to within B-cell lymphomas." (PMID 25880212, 2015). "Aberrant promoter methylation of SOX11 has been reported in most mature B-cell lymphomas except MCL, which express SOX11 and where SOX11 has functional and prognostic roles." (PMID 25880212, 2015). "In agreement with this, SOX11 has been reported to be strongly methylated in most B-cell lymphomas, in nasopharyngeal carcinomas and in bladder cancer." (PMID 25880212, 2015). "Four B cell lymphoma cell lines expressing varying amounts of SOX11 were used and included Z138, SP53, GRANTA-519 and JEKO-1." (PMID 22738398, 2012). "As previously shown for B cell lymphoma cell lines, the protein and mRNA expression of SOX11 in ovarian cancer cell lines correlated with the methylation status of the SOX11 promoter region." (PMID 21943380, 2011). "To further clarify if SOX11 is the limiting factor in a signaling cascade or if SOX11 possibly exhibits a master regulatory property, we overexpressed SOX11 in different B cell lymphoma cells lines with variable degree of wild-type SOX11 expression." (PMID 20624318, 2010). "To date, a number of biomarkers with a diagnostic value for each B-cell lymphoma subtype have been determined: BCL2, BCL6, CD10, CD21, and STMN1 in FL; D1 and SOX11 in MCL; FOXP1 and MUM1 in ABC-DLBCL; CD10, BCL2, BCL6, LMO2, and GCET1 in GC-DLBCL; and CD30, CD15, EBV, BOB1, OCT2, and CD79a in HL." (PMID 37894763, 2023). "SOX11 expression has also been reported in a fraction of other T and B-cell lymphomas, including B- and T-cell lymphoblastic lymphomas and a subset of Burkitts lymphoma, but the most common B-cell lymphomas lack SOX11 expression." (PMID 22738398, 2012). "Furthermore, the tumour suppressor function of SOX11, as previously reported for B cell lymphomas, was now extended to EOC and demonstrated through transient over-expression of SOX11." (PMID 21943380, 2011). "The difference in response to SOX11 overexpression comparing different cell lines may be related to the need of co-factors, as the strongest effect was seen in cell lines which already expressed SOX11, as also has been reported for B cell lymphomas." (PMID 21943380, 2011). "Furthermore, promoter analysis revealed that SOX11 is silenced through DNA methylation in B cell lymphomas, suggesting that its regulation is epigenetically controlled." (PMID 20624318, 2010). "Analysis of the SOX11 promoter identified the presence of CpG islands, and bisulfite sequencing demonstrated a strong correlation between promoter methylation status and SOX11 mRNA and protein levels in both B cell lymphoma cell lines and primary tumors." (PMID 20624318, 2010).
B-cell lymphomas (continued). "Additionally, SOX11 promotes PAX5 expression, which in turn blocks plasmacytic differentiation, locking the cell in the mature B-cell stage, and has been previously implicated as an oncogenic mechanism in other B-cell lymphomas." (PMID 34888236, 2021). "The standardization of treatment and diagnosis, especially the extensive use of immunohistochemical markers such as CyclinD1 and Sox11, make it helpful to discriminate MCL from other B‐cell lymphomas." (PMID 37148540, 2023). "Furthermore, SOX11 may be expressed in other aggressive B cell lymphomas that lack cyclin D1." (PMID 21124928, 2010). "MRQ-58 has been applied in the study of SOX11 and B cell lymphoma because it has been proven to be the most sensitive marker and does not cross-react with the SOX4 protein, which has high amino acid sequence similarity with SOX11." (PMID 34256839, 2021). "SOX11 expression can help distinguish MCL from other B cell lymphomas like chronic lymphoid leukemia (CLL) as most of them do not stain for SOX11." (PMID 26949534, 2016). "Others have recently shown that SAHA treatment used in combination with 5-Aza-dC increase the expression of SOX11 in a negative B cell lymphoma cell line." (PMID 21943380, 2011). "In agreement with the in vitro data a difference in DNA methylation status of the SOX11 promoter was evident between expressing and non-expressing primary B cell lymphomas." (PMID 20624318, 2010). "The absence of CD10, CD30, SOX11 and Cyclin D1 help rule out other B-cell lymphoma." (PMID 40896441, 2025). "However, there are no data on the role of SOX genes in microglia in which Sox11 is expressed in the cytoplasm as reported in plasma myeloma cells and other B-cell lymphomas." (PMID 22697290, 2012). "In the rest of the neoplasms studied, including additional ALL groups and mature B-cell neoplasms such as CLL, FL, iMCL, DLBCL, primary mediastinal B-cell lymphoma and BL, SOX11 was either not expressed or expressed at very low levels in a small subset of the cases." (PMID 21738649, 2011). "Furthermore, methylation-dependent silencing of SOX11 has been reported for B cell lymphomas and indicates that epigenetic drugs may be used to re-express this tumour suppressor, but information on SOX11 promoter methylation in EOC is still lacking." (PMID 21943380, 2011). "A repeat AC paracentesis was performed for cytological analysis, which revealed monoclonal B-cell lymphoma population positive for CD20, CD5, cyclin D1, and SOX11 but negative for CD10, CD3, and S100." (PMID 26450638, 2015).
ovarian carcinoma (17 papers, 2011 to 2025). A malignant neoplasm originating from the surface ovarian epithelium. "However, in other cancer types, including other hematological cancers, and epithelial ovarian cancer, SOX11 is frequently methylated and high SOX11 expression is associated with improved survival." (PMID 26894864, 2016). "However, other studies in ovarian cancer and in gastric cancer have found that elevated SOX11 is associated with improved outcome, and that SOX11 can act as a tumor suppressor." (PMID 26894864, 2016). "The presence of SOX11 is associated with improved recurrence-free survival (RFS) in ovarian cancer." (PMID 24604109, 2014). "The journal retracts the article titled “MicroRNA-223-3p Regulates Ovarian Cancer Cell Proliferation and Invasion by Targeting SOX11 Expression”, cited above." (PMID 40332482, 2025). "As far as SOX11 is concerned, only four study groups have to date examined the role of SOX11 as an epithelial ovarian cancer biomarker in terms of tumor metastasis and patient survival." (PMID 37760985, 2023). "The gene SOX11 was identified and validated in an independent dataset as a prognostic marker in ovarian cancer." (PMID 37761986, 2023). "The upregulated miR-223-3p enhances the cell proliferation, migration, and invasion in ovarian cancer by targeting SOX11." (PMID 35647303, 2022). "It was found that miR-223-3p inhibitor restrains ovarian cancer development by increasing SOX11 expression." (PMID 30134837, 2018). "We and others have during recent years shown that SOX11 is a diagnostic, prognostic, and functional biomarker in classical MCL, indolent MCL, ovarian cancer and astrocytic gliomas." (PMID 25880212, 2015). "Consistent with previous finding which showed SOX11 as a tumor-suppressor in ovarian cancer, we found SOX11 was correlated with less malignant features in gastric cancer." (PMID 24604109, 2014). "Here, we were able to demethylate the SOX11 promoter in the ovarian cancer cell line ES-2, resulting in a successful expression of SOX11 mRNA and protein." (PMID 21943380, 2011). "The neural transcription factor SOX11 has been described as a prognostic marker in epithelial ovarian cancers (EOC), however its role in individual histological subtypes and tumour grade requires further clarification." (PMID 21943380, 2011). "miR-223-3p has been characterized as a oncogene in multiple tumors, such as pancreatic cancer, prostate cancer, ovarian cancer, lung cancer and gastric cancer, by targeting different genes, such as FBXW7, SEPT6, SOX11, EPB41L335–38." (PMID 29317648, 2018). "Kaplan-Meier analysis and the log rank test were applied to evaluate ovarian cancer-specific survival (OCSS) and overall survival (OS) in strata, according to SOX11 expression." (PMID 21943380, 2011). "The SOX11 negative epithelial ovarian cancer cell line ES-2 is methylated in the SOX11 promoter region." (PMID 21943380, 2011). "Thus, SOX11-negative ovarian cancer cell lines are specifically silenced by DNA methylation that at least partly can be reversed by demethylating drugs." (PMID 21943380, 2011). "In particular, the poor prognostic value of SOX11 expression in pancreatic cancer and sarcoma and SOX12 expression in breast and ovarian cancer as well as sarcoma, has not been reported previously." (PMID 34442467, 2021).